LINC01565 (long independently transcribed non-coding RNA 1565)
Synonyms: C3orf27; GR6
Gene: Long non-coding RNA gene on chromosome 3 (128,565,094 to 128,576,086, reverse strand). Ensembl gene ENSG00000198685.
Diseases named in the same sentence as LINC01565 in open-access papers:
LINC01565 is named in the same sentence as 4 diseases in open-access papers, as found by Europe PMC text mining. Sharing a sentence is not in itself a finding about the gene and the disease.
LINC01565 shares sentences with these, for which no sentence is quoted: tumor (2 papers); cancer (1); lung adenocarcinoma (1); non-small cell lung carcinoma (1).